SEMA7A (semaphorin 7A (JohnMiltonHagen blood group))
Description:
Plays an important role in integrin-mediated signaling and functions both in regulating cell migration and immune responses. Promotes formation of focal adhesion complexes, activation of the protein kinase PTK2/FAK1 and subsequent phosphorylation of MAPK1 and MAPK3. Promotes production of pro-inflammatory cytokines by monocytes and macrophages. Plays an important role in modulating inflammation and T-cell-mediated immune responses. Promotes axon growth in the embryonic olfactory bulb. Promotes attachment, spreading and dendrite outgrowth in melanocytes.
Synonyms: CD108; SEMAL; H-Sema-L; CDw108; H-SEMA-K1; JMH; PFIC11; SEMAK1
Tractability: Small molecule: it has a high-quality binding pocket. Antibody: UniProt places it where antibodies can reach, with high confidence; its Gene Ontology location is reachable by antibodies, with high confidence; UniProt predicts a signal peptide or a membrane-spanning region. PROTAC: its protein half-life has been measured.
Gene: Protein-coding gene on chromosome 15 (74,409,289 to 74,433,958, reverse strand). Ensembl gene ENSG00000138623.
Subcellular location: Cell membrane
Subcellular location (Human Protein Atlas): Vesicles
Pathways (Reactome):
Developmental Biology: Other semaphorin interactions
Gene Ontology:
Molecular function: protein binding; chemorepellent activity; integrin binding; neuropilin binding; semaphorin receptor binding
Biological process: integrin-mediated signaling pathway; osteoblast differentiation; positive regulation of axon extension; positive regulation of ERK1 and ERK2 cascade; axon guidance; immune response; negative chemotaxis; neural crest cell migration; positive regulation of cell migration; positive regulation of macrophage cytokine production; regulation of inflammatory response; semaphorin-plexin signaling pathway; regulation of synapse maturation
Cellular component: extracellular matrix; membrane; external side of plasma membrane; plasma membrane; GABA-ergic synapse; presynapse
Genetic constraint (gnomAD): Loss-of-function variants: 22 observed, 70.22 expected, observed/expected ratio (o/e) 0.31, 90% interval 0.22 to 0.45. The upper end of that interval is the gene's LOEUF score, 0.45, which puts it in group 1 of 6, group 1 being the genes least tolerant of losing a copy. Missense variants: 774 observed, 908.96 expected, observed/expected ratio (o/e) 0.85, 90% interval 0.8 to 0.9. Synonymous variants: 364 observed, 360.53 expected, observed/expected ratio (o/e) 1.01, 90% interval 0.93 to 1.1.
Homologues: Orthologues: chimpanzee SEMA7A (99% identical), macaque SEMA7A (98% identical), mouse Sema7a (89% identical), rat Sema7a (89% identical), dog SEMA7A (88% identical), pig SEMA7A (83% identical), guinea pig SEMA7A (80% identical). Paralogues in human: SEMA3B (26% identical), SEMA3E (26% identical), SEMA4B (26% identical), SEMA4G (25% identical), SEMA3A (25% identical), SEMA3F (25% identical), SEMA3G (25% identical), SEMA4F (24% identical), SEMA3D (24% identical), SEMA5A (24% identical), SEMA3C (24% identical), SEMA4C (24% identical), and 7 more.
Diseases named in the same sentence as SEMA7A in open-access papers:
SEMA7A is named in the same sentence as 123 diseases in open-access papers, as found by Europe PMC text mining. Sharing a sentence is not in itself a finding about the gene and the disease. The quoted sentences say what the papers report.
breast carcinoma (26 papers, 2014 to 2026). "We previously reported from available genomic databases that SEMA7A mRNA expression is increased and associated with worse prognosis in breast cancer." (PMID 33088913, 2020). "Moreover, high expression of SEMA7A has been associated with significantly decreased patient survival in ER + breast cancer patients." (PMID 40647379, 2025). "Another semaphorin consistently implicated in breast cancer development is Sema7A." (PMID 33537086, 2021). "Moreover, the association of elevated Sema7A and macrophage markers predicted shorter distant metastasis-free survival in a large cohort of breast cancer patients." (PMID 33537086, 2021). "Our data suggest a mechanism linked through the increase of SEMA7A mediated lymphangiogenesis occurring during normal postpartum breast involution that can durably affect breast cancers arising in the subsequent 5 years after childbirth and associates with the unique poorer outcomes of PPBC." (PMID 33088913, 2020). "Thus, in addition to Sema4C, Sema7A could represent another potential therapeutic target and a predictive biomarker for ER+ breast cancer patients at high risk for resistance to hormonal therapy and metastatic relapse." (PMID 33537086, 2021). "Finally, SEMA7A has a functional role in lymphatic vessel modulation, as we recently published that SEMA7A promotes tumor-associated lymphangiogenesis via macrophage-mediated lymphatic vessel remodeling during postpartum involution and breast cancer." (PMID 30847405, 2019). "SEMA7A induces epithelial to mesenchymal transition, and promoting metastasis in melanoma, glioblastoma, oral, kidney and breast cancers." (PMID 40647379, 2025). "It has been shown that in murine models, the silencing of SEMA7A resulted in the impaired angiogenesis, migration, proliferation, and invasiveness of breast cancer." (PMID 39329961, 2024). "SEMA7A is reported to be hormonally regulated in breast cancer; however, SEMA7A is expressed independently of oestrogen stimulation." (PMID 37685898, 2023). "Other metastases genes associated with poor prognosis in breast cancer, such as CEACAM6, COL17A1, CXCL8, TNFAIP3, SEMA7A and L1CAM, are also attenuated with SP receptor antagonist treatment." (PMID 34359773, 2021). "Though elevated SEMA7A is observed in breast cancer, where we have established a role for it in conferring cell survival, in part, via promotion of anoikis resistance, the role of SEMA7A in normal MECs has not previously been investigated." (PMID 34561423, 2021). "Sema7A has pro-angiogenic properties, can contribute to the metastasis of breast cancer cells by inducing EMT and was reported to be overexpressed in oral SCC, where the proliferation and invasiveness of cancer cells are enhanced." (PMID 35008571, 2021). "Despite published roles for SEMA7A in breast cancer progression, the current study is, to our knowledge, the first investigation into the role of SEMA7A in normal MEC survival during postpartum mammary gland involution." (PMID 34561423, 2021). "This indicates a role for SEMA7A overexpression in the normal-adjacent postpartum breast leading to a commensurate enduring overexpression of SEMA7A in the developing breast cancers." (PMID 33088913, 2020). "Specifically, SEMA7A expression was observed to be highest in PPBC patients that had subsequently faced a breast cancer recurrence with local-regional or metastatic disease." (PMID 33088913, 2020). "Further study into SEMA7A as a prognostic biomarker and potential therapeutic target for this deadly subset of breast cancer are warranted and ongoing." (PMID 33088913, 2020). "In preclinical murine models, semaphorin 7a (SEMA7A) drives the metastatic potential of postpartum mammary tumors." (PMID 33088913, 2020). "Further, implantation of Sema7A gene-silenced mammary tumor cells resulted in decreased in vivo tumor angiogenesis compared to the wild type tumors." (PMID 32210960, 2020).
breast carcinoma (continued). "This is further supported by the prognostic value of a combined genetic signature of CD68, PDPN, and SEMA7A in predicting decreased distant metastasis free survival in a cohort of 600 human breast cancer cases." (PMID 30847405, 2019). "In agreement, Sema7a gene expression is observed in a high frequency in human breast cancer and correlates with metastasis and poor prognosis." (PMID 31024552, 2019). "SEMA7A can also promote angiogenesis in a hypoxia-independent manner in murine mammary carcinoma and in the cornea by stimulating macrophages to produce pro-angiogenic molecules, such as CXCL2/MIP-2 and VEGF-A." (PMID 30847405, 2019). "In order to understand the role of Sema7A in breast cancer progression, its expression levels were determined for normal breast tissues and compared with invasive ductal carcinomas (IDC) using the TCGA dataset and Oncomine software." (PMID 30134791, 2018). "Sema7A in mammary carcinomas induces macrophages to secret chemokines such as CXCL2/MIP-2 to support angiogenesis in the tumors However, the cellular basis of Sema7A receptors and the molecular mechanisms were not fully described." (PMID 30555351, 2018). "In the tumor study, Sema7A was highly expressed in murine mammary tumor cells and peritoneal elicited macrophages." (PMID 30555351, 2018). "Previous reports showed that Sema7A induces neovascularization in corneal fibroblasts and murine mammary tumor cells." (PMID 30555351, 2018). "In this study we explore the role of SEMA7A in breast cancer progression using the DA-3 mammary tumor model." (PMID 24550834, 2014). "Analysis of total protein from supernatants of 3 day DA-3 mammary tumor cell cultures confirmed the soluble protein expression of SEMA7A, with increased levels reflected by increased cell numbers." (PMID 24550834, 2014). "qPCR revealed very low levels of SEMA7A expression in EpH4 cells compared to DA-3 mammary tumor cells." (PMID 24550834, 2014). "More recently, SEMA7A has been reported to be a protumor factor that promotes the progression of multiple cancers, such as melanoma, oral cancer, breast cancer and glioma by promoting the proliferation, invasion and migration of tumor cells as well as the epithelial-to-mesenchymal transition." (PMID 41019072, 2025). "It has been reported that SEMA7A contributes to tumor metastasis via promoting extracellular matrix adhesion or alluring epithelial-mesenchymal transition in oral cancer, melanoma and breast cancer." (PMID 40936767, 2025). "Indeed, SEMA7A has been found to be highly expressed in the tumor cells and tumor tissues of patients with breast carcinoma." (PMID 41019072, 2025). "Finally, SEMA7A has been suggested as a biomarker for BC recurrence specifically in patients with postpartum breast cancers (PPBCs; defined as BC in women within 10 years of most recent childbirth)." (PMID 37685898, 2023). "SEMA7A overexpression has also been reported to confer resistance to tyrosine kinase inhibitor (TKI) treatment in EGFR mutant lung cancers, associating SEMA7A both with TKI resistance in lung and endocrine therapy resistance in breast cancer." (PMID 37685898, 2023). "Elder and Tamburini found that Sema7A might be involved in macrophage-mediated lymphangiogenesis in breast cancer." (PMID 35155237, 2022). "Therefore, CD68, Sema7A, and PDPN are associated with poor prognosis of breast cancer patients with lymphatic metastasis." (PMID 35155237, 2022). "Although Sema7A has a stimulating effect on the maturation and antigen presentation of DCs, which is beneficial for immune response, a growing number of studies have shown that Sema7A/integrin β1 is a promigratory signal and confers poor survival rate in glioma and breast cancer." (PMID 35155237, 2022). "To test whether SEMA7A promotes chemoresistance in breast cancer cells, we treated SEMA7A-overexpressing and knockdown MCF10DCIS mammosphere cultures with the chemotherapeutic drug, paclitaxel." (PMID 34561423, 2021).
breast carcinoma (continued). "Therefore, we predict that SEMA7A promotes cellular transformation and tumor initiation in breast cancer patients and, in particular, in PPBC patients." (PMID 34561423, 2021). "Using an antibody raised against amino acids 371–441 in the SEMA7A protein sequence, which will recognize all isoforms of SEMA7A due to sequence homology, we compared SEMA7A expression with multiple breast cancer clinical characteristics that are known prognostic indicators across all 113 cases." (PMID 33088913, 2020). "Targeting SEMA7A in conjunction with already established therapies, such as NSAIDs, may also increase the efficacy of these treatments in women with breast cancer." (PMID 30847405, 2019). "The complex interplay between integrins, collagen, COX-2, and SEMA7A is, thus, likely to be context-dependent, and additional studies are necessary to understand the role of this signaling axis in mediating tumor cell invasion and metastasis in breast cancer." (PMID 30847405, 2019). "Cumulatively, the presented data suggest that Sema7A-related therapies could be beneficial for breast cancer patients." (PMID 30134791, 2018). "Moreover, there was a direct correlation between Sema7A levels and early cancer recurrence, metastasis, and patients’ patient’s deaths in multiple publicly available datasets for breast cancer patients." (PMID 30134791, 2018). "In contrast, recent studies have reported that SEMA7A was overexpressed in breast cancer, melanoma, and glioblastoma and may contribute to tumoral cell migration and tissue remodeling in the tumoral microenvironment." (PMID 26378920, 2015). "The biological role of SEMA7A in breast cancer progression was explored in this study." (PMID 24550834, 2014). "We are the first to show that SEMA7A plays a role in breast cancer progression." (PMID 24550834, 2014). "We postulate that SEMA7A in mammary carcinomas may skew monocytes into a pro-tumorigenic phenotype to support tumor growth." (PMID 24550834, 2014). "In this study we explored the role of SEMA7A in a murine model of breast cancer." (PMID 24550834, 2014). "First, we find that SEMA7A is expressed by mammary tumor cells." (PMID 24550834, 2014). "We show that SEMA7A is highly expressed by DA-3 murine mammary tumor cells in comparison to normal mammary cells (EpH4), and that peritoneal elicited macrophages from mammary tumor-bearing mice also express SEMA7A at higher levels compared to those derived from normal mice." (PMID 24550834, 2014). "Second, we show that SEMA7A expression is upregulated in macrophages of mammary tumor-bearing mice." (PMID 24550834, 2014). "We hypothesized that silencing SEMA7A gene in DA-3 mammary tumor cells would result in decreased secretion of SEMA7A in tumor cell cultures and treatment of macrophages with this conditioned media would therefore have a negative influence on their migration." (PMID 24550834, 2014). "As shown in the previous section, DA-3 mammary tumor cells express and shed SEMA7A." (PMID 24550834, 2014). "Using immunohistochemistry and an AngioSense probe, an in vivo blood pool vascular fluorescent imaging agent, we determined the in vivo role of SEMA7A by comparing angiogenesis in mice bearing scramble shRNA DA-3 mammary tumors with those bearing SEMA7A shRNA knockdown DA-3 mammary tumors." (PMID 24550834, 2014). "We are the first to clearly demonstrate that SEMA7A is expressed by mammary tumor cells." (PMID 24550834, 2014). "Thus, thioglycollate peritoneal elicited macrophages from normal (N-PEMs) and DA-3 mammary tumor-bearing mice (DA-3 PEMs) were therefore tested to determine SEMA7A expression." (PMID 24550834, 2014). "Moreover, sema7a induces gp38 upregulation by tumor-infiltrating macrophages, therefore promoting their adhesion to LVs and consequently boosting lymphangiogenesis and metastasis in breast cancer." (PMID 31024552, 2019). "Additionally, tumor-promoting functions have been described for Sema7A in breast cancer." (PMID 29141914, 2018).
breast carcinoma (continued). "In addition, the authors identified a novel stimulatory role for Sema7A in lymphangiogenesis and defined the mechanism of Sema7A action in breast cancer as being regulated by COX-2 and activating β1-integrin receptor expression, which mediated tumor cell invasiveness." (PMID 30134791, 2018). "Thus, SEMA7A gene was silenced in DA-3 mammary tumor cells by shRNA." (PMID 24550834, 2014). "Sema7A promotes macrophages podoplanin (PDPN) expression, migration, and adhesion of the lymphatic epithelial cell, resulting in breast cancer lymphatic metastasis." (PMID 35155237, 2022). "Previously published results indicate overall survival is generally decreased for breast cancer patients with high collagen, COX-2, and SEMA7A expression, suggesting that these mechanisms are important mediators of breast cancer metastasis." (PMID 30847405, 2019). "Given that SEMA7A is known to induce CXCL2/MIP-2, and PEMs from DA-3 mammary tumor bearers have increased CXCL2/MIP-2 and SEMA7A, we silenced the SEMA7A gene in DA-3 PEMs using shRNA." (PMID 24550834, 2014). "In this study, we report that peritoneal elicited macrophages from mammary tumor-bearing mice express higher levels of β1 integrins as well as its ligand SEMA7A compared to the control mice in tumor bearers' macrophages, suggesting that SEMA7A could function in a paracrine manner." (PMID 24550834, 2014). "In addition to the feedback between COX-2 and collagen deposition in involution and in breast cancer, we have also published a connection between COX-2 and tumor cell invasion through expression of the neuronal guidance protein, SEMA7A." (PMID 30847405, 2019). "Semaphorin 7a (SEMA7A), cyclooxygenase-2 (COX-2), and collagen are all expressed in the involuting mammary gland and, together, predict for decreased metastasis free survival in breast cancer." (PMID 30847405, 2019). "There are no studies to date describing the expression of SEMA7A in macrophages of mammary tumor bearers." (PMID 24550834, 2014). "To test our hypothesis that SEMA7A plays a role in progression of DCIS in patients, we examined SEMA7A expression in Early Stage Breast Tumors (SCAN-B) for breast cancers by biopsy type and found that SEMA7A mRNA is upregulated in invasive carcinomas compared to in situ carcinomas." (PMID 40470186, 2025). "Interestingly, while individual expression of each molecule does not predict for metastasis using KM Plotter analysis, the combination of high SEMA7A, COX-2, and COL1A1 mRNA expression results in significantly decreased distant metastasis free survival for breast cancer patients in this dataset." (PMID 30847405, 2019).